CTBP1 (C-terminal binding protein 1)
Diseases named in the same sentence as CTBP1 in open-access papers (continued):
Sharing a sentence is not in itself a finding about the gene and the disease.
melanoma (continued). "To define the role of CtBP1 in melanoma more clearly we performed a screening for CtBP1 target genes." (PMID 19216735, 2009). "To get more information about the relevance of the genes found to be regulated by CtBP1 for malignant melanoma we used DNA microarray data obtained from proliferative and invasive phenotype cultures." (PMID 19216735, 2009). "Recently, we showed that CtBP1 expression is lost or strongly reduced in malignant melanoma leading to induction of MIA expression." (PMID 19216735, 2009). "We recently revealed that CtBP1 expression is lost in melanoma cells and melanoma inhibitory activity (MIA) expression is subsequently increased." (PMID 19216735, 2009). "To understand the effect of CtBP1 we identified putative LEF/TCF target genes found to be strongly expressed in melanoma using DNA microarray analysis." (PMID 19216735, 2009). "We have thus evaluated whether Comp. can affect melanoma cell migration and invasion by reverting the transcription of these CtBP1/BARS-controlled EMT-related genes." (PMID 38711119, 2024). "This combination of effects impairs melanoma tumor growth in mouse models providing substantial evidence that pharmacological targeting of CtBP1/BARS may be a feasible strategy for future development of novel melanoma treatments." (PMID 38711119, 2024). "Furthermore, the constitutive expression of these peptides can reverse CtBP1‐mediated oncogenic phenotypes in a melanoma model in both cell culture and mice." (PMID 29879296, 2018). "To determine whether these peptides can limit tumor growth induced by CtBP1 in vivo, we performed a tumor xenograft growth assay using stably transfected mouse melanoma B16‐F0 cells expressing vector control, Pep1‐E1A‐WT, or Pep1‐E1A‐EL." (PMID 29879296, 2018). "CtBP1 has been shown to be overexpressed in melanoma and is important for melanoma development." (PMID 29879296, 2018). "As full length CtBP1 expression is lost in melanoma we hypothesized that CtBP1 acts as a tumor suppressor by negatively regulating genes involved in melanoma development and progression." (PMID 19216735, 2009). "Genes were chosen showing at least one LEF/TCF binding site as these may be activated if repression by CtBP1 is lost in melanoma and wnt signaling is activated." (PMID 19216735, 2009). "The downregulation of full length CtBP1 in melanoma was previously shown." (PMID 19216735, 2009). "Sequence analysis and expression profile of CtBP1 in melanoma cell lines were done by PCR." (PMID 19216735, 2009). "In previous work we could show that CtBP1 functions as a strong repressor of melanoma inhibitory activity (MIA) expression by negatively regulating MIA promoter activity in malignant melanoma, and that this repressor function requires the TCF binding element in the MIA promoter." (PMID 19216735, 2009). "CtBP1/BARS is also involved in genome instability through its transcriptional regulation of BRCA1 gene, which dampens DNA-damage repair in melanoma." (PMID 38711119, 2024). "The transwell invasion assays also showed that Comp. or CtBP1/BARS siRNAs treatment inhibited cell invasion, indicating an inhibitory role of CtBP1/BARS bound to Comp. on melanoma cell invasion." (PMID 38711119, 2024). "Lastly, to investigate a potential role of CTBP1 in regulating CD8 cells in cancer immunotherapy, we analyzed scRNA-seq data from TILs of patients with melanoma treated with ICB." (PMID 38490212, 2024). "This study identifies a potent and selective inhibitor of CtBP1/BARS active in cellular and melanoma animal models revealing new opportunities to study the role of CtBP1/BARS in tumor biology and to develop novel melanoma treatments." (PMID 38711119, 2024).
melanoma (continued). "Having established the more pronounced expression levels of CtBP1/BARS in the two A375MM and B16F10 melanoma cell lines, we investigated the cytotoxic effects of Comp. on these cells (and compared these effects with those of MTOB, HIPP and PPγ inhibitors)." (PMID 38711119, 2024). "Altogether, these data suggest that Comp.11, with the best results at the dosage of 20 mg/kg, once bound to CtBP1/BARS, inhibits growth of melanoma tumor in xenograft models, indicating its potential effective antitumor activity." (PMID 38711119, 2024). "In light of this finding, we investigated the possibility that by blocking CtBP1/BARS functions with Comp.11, we could prevent melanoma progression by increasing the BRCA1/BRIP1-controlled DNA-Damage Response Pathway." (PMID 38711119, 2024). "Conversely, MTOB, HIPP and PPγ are not able to antagonize the CtBP1/BARS-regulated activities in melanoma." (PMID 38711119, 2024). "Indeed, in melanoma patients, the increased expression level of CtBP1/BARS correlates with decreased expression and function of BRCA1, and this contribute to genome instability and melanoma initiation." (PMID 38711119, 2024). "The E1a–CtBP1/BARS interaction is required for expression of epithelial gene involved in intercellular adhesion, e.g., desmoglein 2, plakoglobin and E-cadherin, as shown in melanoma cells." (PMID 38711119, 2024). "AS product of CTBP1 is correlated with cell proliferation and migration in melanoma, and full length of CTBP1 do not show difference." (PMID 35860803, 2022). "Various transcriptional regulators have been postulated to be responsible for this effect such as increased binding of the positive factor FOXD3 in melanoma or decrease binding of the negative factor CTBP1 in thyroid cancer." (PMID 26208478, 2015). "MMP7 was found to be down regulated 5-fold by CtBP1 in melanoma, whereas c-myc and laminin gamma 2 were not affected." (PMID 19216735, 2009). "By co-immunoprecipitation we detected TCF4 and Snail binding to full length CtBP1 (in the CtBP1-expressing melanoma cell clones), but none with CtBP1splice." (PMID 19216735, 2009). "Overall, our data indicate that Comp. directly binds to CtBP1/BARS and thus inhibits the transcriptional complex function of CtBP1/BARS shifting gene expression patterns from mesenchymal to a more epithelial phenotype, leading to an impairment of melanoma cell migration and invasion." (PMID 38711119, 2024).
osteosarcoma (12 papers, 2014 to 2025). A usually aggressive malignant bone-forming mesenchymal neoplasm, predominantly affecting adolescents and young adults. "HIPK2 phosphorylates CtBP1 and cause its degradation, thereby inducing the expression of proapoptotic genes in osteosarcoma cells." (PMID 33613771, 2021). "It is also known that CtBP1 plays a critical role in regulating cell proliferation and apoptosis in a variety of cancers, including breast, ovarian, and osteosarcoma." (PMID 37762332, 2023). "A study on osteosarcoma also reported that the expression level of FOXO3a was significantly reduced, and the CtBP1-p300-FOXO3a transcription complex can inhibit the expression of apoptosis regulators in human osteosarcoma cells." (PMID 36823640, 2023). "The abolition of CtBP1 transrepression increased the expression of proapoptotic genes to induce apoptosis and increase chemosensitivity in osteosarcoma cells." (PMID 33613771, 2021). "For example, in osteosarcoma cells, CtBP1 is overexpressed and the resulting CtBP1-p300-FOXO3a complex controls the expression of two proapoptotic genes BAX and BIM7." (PMID 33613771, 2021). "We observed a significant decrease in the expression levels of HIPK2 and phosphorylated CtBP1 in both osteosarcoma cells and biopsies and an opposite response in the CtBP1 expression level." (PMID 33613771, 2021). "The average mRNA level for CtBP1 indicated significant overexpression in osteosarcoma biopsies compared to controls." (PMID 33613771, 2021). "CtBP1 overexpression is observed in multiple cancer types, such as melanoma, osteosarcoma, colon cancer, and prostate cancer." (PMID 33391445, 2021). "The findings presented here revealed a significant downregulation of HIPK2 in both osteosarcoma cell lines and biopsies, as well as an impairment of CtBP1 phosphorylation and a consequent accumulation of CtBP1." (PMID 33613771, 2021). "A previous publication has reported significant overexpression of CtBP1 in osteosarcoma cells." (PMID 33613771, 2021). "We examined whether the overexpression of CtBP1 mRNA and protein levels in osteosarcoma cells was directly regulated by HIPK2 by generating HIPK2-overexpression (OE) cell lines in hFOB1.19, MG63 and Saos2 backgrounds." (PMID 33613771, 2021). "We also determined whether osteosarcoma biopsies had the similar expression patterns for CtBP1, CtBP2 and HIPK2 in 20 osteosarcoma biopsies and their adjacent noncancerous tissues." (PMID 33613771, 2021). "Taken together, our in vitro and in vivo results revealed that overexpression of HIPK2 could remove the CtBP1-mediated transrepression of proapoptotic genes, indicating a new therapeutic option for the treatment of osteosarcoma." (PMID 33613771, 2021). "However, we identified overexpression of CtBP1 mRNA level in osteosarcoma cells and biopsies." (PMID 33613771, 2021). "However, the upstream regulatory signaling of the CtBP1-p300-FOXO3a complex is obscure, and the effects of changing this signaling on chemosensitivity in osteosarcoma are unknown." (PMID 33613771, 2021). "We then determined the protein levels of CtBP1, pCtBP1, CtBP2 and HIPK2 in osteosarcoma cells and biopsies." (PMID 33613771, 2021). "By contrast, the levels of phosphorylated CtBP1 and HIPK2 protein levels were decreased in osteosarcoma cells and they showed the similar patterns in the same osteosarcoma cells." (PMID 33613771, 2021). "Future studies will focus on the possible CtBP1 dependence of the downregulation of CDH1, BAX, BIM, and PTEN in osteosarcoma CSCs." (PMID 33391445, 2021). "A previous study has indicated that CtBP1 couples with p300 and FOXO3a to regulate the expression of BAX and BIM in osteosarcoma cells." (PMID 33613771, 2021). "We investigated the possible involvement of HIPK2 in the regulation of CtBP1 by examining the mRNA level of HIPK2 in the hFOB1.19 human osteoblast cell line and in the DAN, MG63, HOS, T1-73, 143B, Saos2, and U2OS osteosarcoma cell lines." (PMID 33613771, 2021).
osteosarcoma (continued). "The CtBP1-p300-FOXO 3a complex was found to repress apoptotic regulators Bax and Bim in osteosarcoma cells." (PMID 31951590, 2020). "Although we identified a HIPK2-mediated phosphorylation mechanism in the present study, the mechanism for transcriptional regulation of CtBP1 in osteosarcoma cells is not known." (PMID 33613771, 2021). "In the present study, we revealed that CtBP1 directly interacted with FOXM1, and that the complex docked onto the MDR1 promoter through a specific binding site (5′-GTAAACAA-3′) to activate MDR1 expression in osteosarcoma CSCs." (PMID 33391445, 2021). "The high homology of CtBP1 and CtBP2 led us to speculate that NSM00158 could also target CtBP1, and our results confirmed that NSM00158 targeted CtBP1 and inhibited the transactivation of MDR1, thereby increasing the chemosensitivity of osteosarcoma CSCs." (PMID 33391445, 2021). "Importantly, the knockdown of either CtBP1 or FOXM1 and targeting of the CtBP1-FOXM1 complex members with specific inhibitors, including NSM0018 and NSC95397 for CtBP1, and RCM1 for FOXM1, significantly decreased the MDR1 level and increased the chemosensitivity of osteosarcoma CSCs." (PMID 33391445, 2021). "However, whether HIPK2 functions as a tumor suppressor that phosphorylates CtBP1 to promote the tumorigenesis of osteosarcoma is not known." (PMID 33613771, 2021). "However, the expression status of HIPK2 in osteosarcoma cells is not known, and a role for HIPK2 in the phosphorylation of CtBP1 and tumorigenesis remains to be established in osteosarcoma." (PMID 33613771, 2021). "The CtBP1-p300-FOXO3a complex can specifically repress the expression of two downstream targets, Bax and Bim, but not other known CtBP1 targets such as CDH1 (epithelial Cadherin), PTEN (Phosphatase and Tensin Homolog), and CDKN1A (Cyclin-Dependent Kinase Inhibitor 1A) in human osteosarcoma cells." (PMID 31754335, 2019).
colorectal cancer (11 papers, 2010 to 2025). A primary or metastatic malignant neoplasm that affects the colon or rectum. "CtBP1 is overexpressed in various types of cancer such as breast, lung, liver, and colorectal cancers, and its upregulation is linked to worse clinical outcomes, including increased tumor growth, invasion, and metastasis, as well as poor response to chemotherapy and radiation therapy." (PMID 37762332, 2023). "Together, these findings establish a structural framework for CtBP-mediated regulation of G9a activity and highlight the CtBP1/2-G9a complex as a potential therapeutic target in colorectal cancer." (PMID 41419197, 2025). "Our data highlight CtBP1 as a transcription factor that contributes to positive feedback during the early phases of Wnt signaling and serves as a novel marker for colorectal cancer progression." (PMID 20383323, 2010). "Three key pathways were negatively enriched in CtBP1-KD cells, including epithelial to mesenchymal transition in colorectal cancer, MAPK signaling pathway, and cell cycle, while focal adhesion-PI3K-Akt-mTOR-signaling and integrin-mediated cell adhesion were positively enriched." (PMID 34253710, 2021).
lung carcinoma (9 papers, 2012 to 2025). "Mechanistically, JAC4 reduced the PI3K/AKT overactivation caused by both EGFR overexpression and mutations in NSCLC; JAC4 rescued JWA transcription in lung-cancer cells by binding to CTBP1." (PMID 37240137, 2023). "Contrary to lower JWA expression in lung cancer, CTBP1 was highly expressed in A549, NCI-H1975, and HCC827 lung-cancer cell lines and lung-cancer tissues compared to corresponding controls." (PMID 37240137, 2023). "LINC01426 contributes to clear cell renal cell carcinoma progression by modulating CTBP1/miR-423-5p/FOXM1 axis via interacting with IGF2BP1, and to lung cancer progression via AZGP1 and predicts poor prognosis in patients with LUAD." (PMID 35818395, 2022). "Therefore, JAC4 may interact with CTBP1 and block its transcriptional-repressor function on the JWA gene in both HBE and lung-cancer cells." (PMID 37240137, 2023). "Moreover, when CTBP1 was knocked out, its transcriptional suppression on JWA expression was completely removed; therefore, JAC4 was unable to exert subsequent inhibition of lung-cancer growth and metastasis via the CTBP1-JWA pathway in these CTBP1-deficient cells." (PMID 37240137, 2023). "Therefore, a negative correlation between CTBP1 and JWA expression was identified in human-lung-cancer tissues." (PMID 37240137, 2023).
adenoma (8 papers, 2011 to 2025). A neoplasm arising from the epithelium. "Therefore, following APC loss, CtBP1 contributes to adenoma initiation as a first step, whereas KRAS activation and β-catenin nuclear localization promote adenoma progression to carcinomas as a second step." (PMID 29652830, 2018). "Overexpression of CtBP1 has also been shown to occur in adenomas from familial adenomatous polyposis patients who are hereditary colon cancer patients carrying germline APC mutations." (PMID 30410666, 2018). "Overall, our work supports a mechanism where CTBP1 regulates CNOT3 and that overall CNOT3 perturbation could work in concert with germline APC mutations in advancing adenomas to a more transformed state prior to progression to adenocarcinoma." (PMID 31231471, 2019). "Comparative analysis between adenoma with adenocarcinoma samples showed that ARRB1, CTBP1 and CTBP2 are overexpressed in adenoma." (PMID 40362431, 2025). "ARRB1, CTBP1 and CTBP2 were genes identified based on the top 20 frequently occurring genes and are upregulated in adenoma samples." (PMID 40362431, 2025). "In adenoma, ARRB1, CTBP1 and CTBP2 were overexpressed, suggesting their involvement in early tumorigenesis, whereas in CIS, RPS3A and COL4A5 were overexpressed, suggesting their involvement in the transition from benign to malignant stage." (PMID 40362431, 2025). "Recently, it was shown that β-catenin stabilization and C-terminal binding protein 1 (CtBP1) following APC inactivation contribute to adenoma initiation as the first step, and that KRAS activation and β-catenin nuclear localization act synergistically to promote adenoma progression to carcinoma." (PMID 24212796, 2011). "ARRB1 (p = 2.79 × 10−5), CTBP1 (p = 1.33 × 10−5) and CTBP2 genes (p = 0.0002) exhibited notable upregulation in adenoma, whereas COL1A2 (p = 0.0075), CEBPZ (p = 0.0057), MED10 (p = 0.0196) and PAWR genes (p = 0.00215) showed significant upregulation in adenocarcinoma." (PMID 40362431, 2025).
Ataxia (8 papers, 2020 to 2026). Ataxia refers to impaired coordination of voluntary muscle movement. "There are only 20 published cases with CTBP1 mutations, displaying a phenotype of Hypotonia, Ataxia, Developmental Delay and Tooth enamel defect Syndrome (HADDTS)." (PMID 42123581, 2026). "Whole exome sequencing identified a heterozygous de novo likely pathogenic variant in CTBP1, consistent with the clinical diagnosis of Hypotonia, Ataxia, Developmental Delay, and Tooth Enamel Defect Syndrome." (PMID 41153369, 2025). "A CTBP1 variant associated with extremely rare Hypotonia, Ataxia, Developmental Delay, and Tooth Enamel Defect Syndrome was detected in another patient." (PMID 41153369, 2025). "Transcriptional corepressor CTBP1 in the heterozygous condition with a specific R342W mutation causes prominent neurodevelopmental manifestations, including hypotonia, ataxia, and developmental delays in HADDTS patients." (PMID 41459558, 2025). "In 2016, it was definitively established that variant in the CTBP1 gene, located at chr4:1,205,233–1,242,918 GRCh37/hg19, cause Hypotonia, Ataxia, Developmental Delay, and Dental Enamel Defect Syndrome (HADDTS, MIM:617915)." (PMID 38348454, 2024). "Pathogenic variants in the CTBP1 gene has been shown to cause hypotonia, ataxia, developmental delay and tooth enamel defect syndrome (HADDTS)." (PMID 36341169, 2022). "A specific W342 mutation in the transcriptional corepressor CTBP1 leads to prominent neurodevelopmental manifestations including intellectual disability, ataxia, and hypotonia in affected patients." (PMID 33192249, 2020). "On examination, the patient exhibited clinical features consistent with CTBP1-related hypotonia, ataxia, developmental delay, and tooth enamel defect syndrome (HADDTS)." (PMID 41153369, 2025). "A newly emerging syndrome, hypotonia, ataxia, developmental delay, and tooth enamel defects syndrome (HADDTS) is linked to a de novo heterozygous missense mutation in the CTBP1 gene (NM_001328.2: c.1024C → T, p.Arg342Trp)." (PMID 41459558, 2025). "Hypotonia, ataxia, developmental delay, and tooth enamel defects syndrome (HADDTS) is a recently identified disorder linked to a heterozygous mutation in the C-terminal Binding Protein 1 (CTBP1) transcriptional corepressor." (PMID 41459558, 2025). "Here, we first described a Chinese pedigree with CTBP1 variant, and interestingly the patient developed none of hypotonia, ataxia, and dental enamel defects." (PMID 38348454, 2024). "Hypotonia, Ataxia, Developmental Delay, and Tooth Enamel Defect Syndrome (HADDTS) is an exceptionally rare disorder resulting from a heterozygous variant in the C-terminal binding protein 1 (CTBP1) gene." (PMID 38348454, 2024). "Interestingly, a missense mutation on CtBP1 was found in patients presenting neurodevelopmental deficits (e.g., ataxia, intellectual disability), further supporting the role of CtBP in central nervous system development." (PMID 37060501, 2023).